BMPR2 (bone morphogenetic protein receptor type 2)
Diseases named in the same sentence as BMPR2 in open-access papers (continued):
Sharing a sentence is not in itself a finding about the gene and the disease.
pulmonary arterial hypertension (continued). "Some insight into the pathogenesis of PAH has come from the discovery that heterozygous mutations in the bone morphogenetic protein receptor type 2 gene (BMPR2) are present in many patients with heritable pulmonary arterial hypertension (PAH) and some patients with idiopathic PAH." (PMID 22427841, 2012). "In this study, we investigated the impact of BMPR2 mutations on lung development by generating and analyzing airway and alveolar organoids derived from iPSCs obtained from a patient with BMPR2-related pulmonary hypertension (PH) and gene-corrected control iPSCs." (PMID 40722696, 2025). "In this study, we investigated the effects of BMPR2 mutations on lung development by generating airway and alveolar organoids derived from induced pluripotent stem cells (iPSCs) obtained from patients with BMPR2-related pulmonary arterial hypertension, as well as gene-corrected control iPSCs." (PMID 40722696, 2025). "Furthermore, the FK506 was proved to activate BMPR2 and rescued endothelial dysfunction and reverses pulmonary hypertension." (PMID 37307827, 2024). "Dysfunctional BMPR2 signaling is a key feature of pulmonary hypertension (PH)." (PMID 38674024, 2024). "Previous studies on BMPR2 have often focused on pulmonary arterial hypertension (PAH)." (PMID 39142248, 2024). "Similarly, BM from pulmonary hypertensive BMPR2 heterozygote mice induce PH in a dose-dependent manner and increase the number of donor-derived inflammatory cells in the pulmonary vasculature when transplanted into healthy control mice." (PMID 38028440, 2023). "Loss-of-function mutations in pulmonary arterial hypertension (PAH), such as BMPR2, could be candidates for mRNA-based therapies." (PMID 38075698, 2023). "Clinical and hemodynamic presentations at initial diagnosis for pulmonary arterial hypertension patients with or without BMPR2 genetic variant." (PMID 35811711, 2022). "Pulmonary arterial hypertension (PAH), which belongs to the first group, is a rare complication in HHT and is related to mutations in components of the TGF-β pathway; 75% of these mutations are found in BMPR2." (PMID 36079173, 2022). "It should be noted that high levels of TGFβ1 could induced a significant decrement of BMPR2 in human pulmonary microvascular blood vessel endothelial cells, while BMPR2 reduction sufficiently promotes EndMT in pulmonary arterial hypertension." (PMID 35582418, 2022). "In addition, a previous study reported that BMPR2 expression is reduced in patients with idiopathic pulmonary fibrosis or in those with pulmonary hypertension." (PMID 35714115, 2022). "BMPR2 is involved in growth, differentiation and apoptosis of epithelial and mesenchymal cells during pulmonary vascular smooth muscle hypertrophy and pulmonary vascular remodeling, which results in pulmonary hypertension." (PMID 34793329, 2021). "When endothelial activin-A-bone morphogenetic protein receptor type 2 link is overdriven in mice, hypoxia-induced pulmonary hypertension was exacerbated, whereas conditional knockout of inhibin-β-A in endothelial cells prevents the progression of pulmonary hypertension." (PMID 33741934, 2021). "Alterations in BMPR2 signaling have been shown to affect the microtubules, which is thought to contribute to the pathology of several diseases including hereditary spastic paraplegia, Huntington’s disease, and pulmonary arterial hypertension." (PMID 34563224, 2021). "In the past 5 years, miR-23a has been found to be a biomarker for idiopathic PH and a possible therapeutic target for pulmonary arterial hypertension because it promotes cell proliferation and migration by targeting the BMPR2/Smad1 signal in hypoxia-induced PASMCs." (PMID 34374413, 2021).
pulmonary arterial hypertension (continued). "We did not detect significantly increased lung 18FLT uptake in pulmonary arterial hypertension patients, nor in the unaffected bone morphogenetic protein receptor type 2 mutation carriers, as compared to healthy subjects." (PMID 34276963, 2021). "For example, multiple genes in the AT1 cell program were closely related to pulmonary veno-occlusive disease (PVOD) (Bmpr2 and Eif2ak4), lung cancer (Itga9 and Braf), pulmonary fibrosis (Cadm1 and Itgb6), pulmonary hypertension (Bmpr2 and Cav1), and pulmonary emphysema (Itgb6)." (PMID 34873160, 2021). "Mouse models deficient in BMPR2 exposed LPS were shown to develop evidence of pulmonary hypertension, which did not occur in their wild-type counterparts." (PMID 33224960, 2020). "Some other monogenetic lung disorder-related genes were enriched in specific SAE cell types, including BC (LTBP4, ELN, cutis laxa), ionoctyes (HPS5, Hermansky-Pudlak syndrome), mucin-producing cells (COL1A1, Ehlers-Danlos syndrome), and neuroendocrine cells (BMPR2, pulmonary hypertension)." (PMID 32727470, 2020). "However, lungs of BMPR2 knockout mice showed thickened arterial wall, which is characteristic of pulmonary arterial hypertension." (PMID 32350411, 2020). "The novel BMPR2 mutation we report is extremely dangerous because it not only causes pulmonary hypertension, but also manifests as HHT." (PMID 32756122, 2020). "Intraperitoneal injections of antagomiR-20a significantly down-regulated the expression levels of miR-20a-5p and restored functional levels of bone morphogenetic protein receptor type 2 (BMPR2) in pulmonary arteries in hypoxia-induced pulmonary hypertension mouse model." (PMID 30717412, 2019). "Even pulmonary arterial hypertension patients without BMPR2 mutations often exhibit a reduced expression of BMPR27." (PMID 30272025, 2018). "Although complicated by the selection of a fibroblast-specific promoter, a fibroblast-specific BMPR2 knockout animal model could provide further insight into the role of the adventitia in pulmonary hypertension." (PMID 30149506, 2018). "BMPR2 is known to play a role in pulmonary vascular remodeling in pulmonary hypertension." (PMID 28859128, 2017). "BMPR-II has been implicated previously in leukocyte-endothelial interactions, and BMPR2 deficiency is associated with several inflammatory vascular pathologies including pulmonary arterial hypertension and atherosclerosis." (PMID 28646109, 2017). "Selective enhancement of endothelial BMPR2 with BMP9 reverses pulmonary arterial hypertension." (PMID 26801773, 2016). "Various pathways are likely to generate this protective effect, for example Treg (T regulatory) cells might prevent the development of pulmonary hypertension and margin endothelial injuries, through the upregulation of BMPR2 in lung tissue." (PMID 24739042, 2014). "Research focusing on the pathway of IL-6, involving the action of microRNAs and regulation of the expression of BMPR2 thus is ongoing to extend these findings to other forms of pulmonary hypertension or the use of these factors as surrogate markers for the disease." (PMID 24739042, 2014). "Mice carrying one copy of a mutant Bmpr2 allele lacking exon 2 (Bmpr2ΔE2) do not manifest pulmonary hypertension at baseline but develop more marked pulmonary hypertension after prolonged exposure to hypoxia." (PMID 24116187, 2013). "Our study suggests that exposure with a mild Th2 antigen can trigger pulmonary hypertension on the background of the expression of a hypomorphic BMPR2 gene and that conversely, the expression of the hypomorphic BMPR2 gene can alter the immune response to a mild, inhaled antigen." (PMID 23383100, 2013). "Although the main objective of our work was to study the role of the tail domain of Bmpr2 using cells from Bmpr2Δtd/+ mice, we did examine whether Bmpr2Δtd/+ mice spontaneously develop pulmonary hypertension." (PMID 24116187, 2013).
pulmonary arterial hypertension (continued). "This provides one logical explanation for our finding of reduced BMPR2 gene expression among females compared to males, and may contribute to the significant gender disparity in pulmonary arterial hypertension." (PMID 22348410, 2012). "BMPR2 gene defect is involved in the development of pulmonary arterial hypertension (PAH)." (PMID 19134193, 2009). "BMPR2 mutations are the most common genetic cause of heritable pulmonary arterial hypertension and are associated with earlier onset, more severe disease, and poor response to therapy compared to pulmonary arterial hypertension without BMPR2 mutations." (PMID 42311580, 2026). "However, it has already been demonstrated that SSc patients, even those with associated pulmonary hypertension, do not exhibit BMPR-2 mutations." (PMID 38999801, 2024). "There is compelling evidence that ECFC from pulmonary arterial hypertension patients with BMPR2 mutations exhibit a vasculoproliferative phenotype without the formation of stable vascular networks, highlighting the importance of ECFC in the pathogenesis of PAH." (PMID 38580869, 2024). "Further, genetic defects in BMPR2 are well recognized in pulmonary arterial hypertension (PAH) and are present in IPF, supporting a link between the two disease processes." (PMID 37712420, 2023). "Bone morphogenic protein receptor 2 (BMPR2) expression and signaling are impaired in pulmonary arterial hypertension (PAH)." (PMID 36672250, 2023). "A biomimetic inducible model of pulmonary arterial hypertension (PAH) is presented, combining natural and induced BMPR2 dysfunction with hypoxia in lung endothelial cells and blood-derived PAH cells to induce smooth muscle activation & proliferation." (PMID 36344664, 2022). "However, the role of BMPR2 alternative splicing or long-range regulatory sequences in determining penetrance of heritable pulmonary arterial hypertension remains unclear." (PMID 36497082, 2022). "This suggests that the effectiveness of ANA at reversing pulmonary hypertension in these hypoxic mice is closely related to the effects of hypoxia on lung oestrogen synthesis via aromatase and the direct effects of this endogenous oestrogen on lung pathology and BMPR2 signalling." (PMID 30923189, 2019). "Hence, endogenous oestrogen and increased 16αOHE1 may be synergising with reduced BMPR2 in obese hypoxic mice to contribute to the pulmonary hypertension phenotype." (PMID 30923189, 2019). "Here we show that the receptor BMP type 2 (BMPR2) serves as a central gatekeeper of this balance, highlighted by its deregulation in diseases such as pulmonary arterial hypertension (PAH)." (PMID 31826007, 2019). "Nearly 20 years ago, genetic linkage studies connected Bone Morphogenetic Protein Receptor II (BMPR2) to the development of familial pulmonary arterial hypertension (PAH)." (PMID 30149506, 2018). "Bone morphogenetic protein receptor type 2 (BMPR2) mutations are present in patients with heritable and idiopathic pulmonary arterial hypertension (PAH)." (PMID 28828907, 2017). "Pulmonary arterial hypertension (PAH) is a disease of progressively increasing pulmonary vascular resistance, associated with mutations of the type 2 receptor for the BMP pathway, BMPR2." (PMID 24713633, 2014). "Interleukin-6 (IL-6) and its activation of STAT3 signaling contribute to the pulmonary arterial hypertension (PAH) related to BMPR2 down-regulation." (PMID 19134193, 2009). "Previous pre-clinical studies demonstrated that exogenous administration of recombinant human wild type BMP9 (WT BMP9) enhances BMPR2/ALK1 mediated signaling and reverses experimental pulmonary hypertension in rat models." (PMID 40720495, 2025). "Another experimental study showed that the defect of BMPR2 signaling could also induce pulmonary artery smooth muscle cells to produce inflammatory cytokines, thereby aggravating the inflammatory response and promoting the development of pulmonary hypertension." (PMID 36937903, 2023).
pulmonary arterial hypertension (continued). "BMPR2: bone morphogenetic protein receptor type-2, HIV: human immunodeficiency virus, PAH: pulmonary arterial hypertension." (PMID 37654961, 2023). "Investigations have suggested that BMPR2 and hypoxia-inducible factor (HIF) signalling pathways play a crucial role in the pathogenesis of pulmonary arterial hypertension." (PMID 35033157, 2022). "Decreased or dysfunctional BMPR2 expression increased high mobility group AT-hook 1 (HMGA1) expression, leading to EndMT in PAEC and promoting occlusive remodeling of idiopathic pulmonary hypertension." (PMID 36419957, 2022). "FHIT is however downregulated in human pulmonary arterial hypertension (PAH), and FHIT positively regulates BMPR2 (bone morphogenetic protein receptor type 2), also downregulated in PAH, and important for the development of PAH." (PMID 31538680, 2020). "To examine whether the associations observed were driven by trans effects of known rare pathogenic variants in pulmonary arterial hypertension, we did sensitivity analyses that demonstrated that the associations were independent of BMPR2 and other rare pathogenic variants." (PMID 30527956, 2019). "The bone morphogenic protein receptor 2 (BMPR2) is a member of the transforming growth factor beta (TGFβ) receptor family that has been found to play a significant role in pulmonary arterial hypertension (PAH), obesity, and insulin resistance." (PMID 29922517, 2018). "Mutations in BMP9 and its' receptors underlie vascular diseases, namely hereditary hemorrhagic telangiectasia (ALK1, endoglin, and BMP9) (29, –31) and pulmonary arterial hypertension (ALK1, BMPR2) (32, –34)." (PMID 28646109, 2017). "Serotonergic anorexigens are the primary pharmacologic risk factor associated with pulmonary arterial hypertension (PAH), and the resulting PAH is clinically indistinguishable from the heritable form of disease, associated with BMPR2 mutations." (PMID 26863209, 2016). "Importantly, BMPR2 was required for NOTCH1 activation and deletion of endothelial specific Notch1 in transgenic mice exacerbated hypoxia-induced pulmonary hypertension." (PMID 38791441, 2024). "Importantly, BMPR2 was demonstrated to be required for NOTCH1 activation and deletion of endothelial specific Notch1 in transgenic mice exacerbated hypoxia-induced pulmonary hypertension." (PMID 38903104, 2024). "Deletion of exon 12 is a common consequence of BMPR2 mutation in PAH patients, and mice over-expressing the BMPR2 isoform lacking exon 12 develop pulmonary hypertension." (PMID 38132114, 2023). "In addition, one study reported that BMPR2 gene analysis is indicated in patients affected with both HHT and heritable pulmonary arterial hypertension (HPAH)." (PMID 35209959, 2022). "Furthermore, in idiopathic pulmonary hypertension, HIMF stimulates autophagy and bone morphogenetic protein receptor type 2 (BMPR2) impairment." (PMID 33800244, 2021). "Moreover, other regionalized vascular disorders such as hereditary hemorrhagic telangiectasia (HHT) and pulmonary arterial hypertension (PAH) are mainly caused by mutations in the BMP receptors ACVRL1 (encoding ALK1) or ENG (encoding Endoglin) and BMPR2 respectively." (PMID 27724845, 2016). "Bmpr2+/- mice express about 50% of Bmpr2+ mRNA levels and manifest little or no pulmonary hypertension at baseline; however, pulmonary hypertension induced by an inflammatory stress or an infusion of serotonin is more marked in Bmpr2+/- than in WT mice." (PMID 24116187, 2013). "Idiopathic pulmonary arterial hypertension (IPAH), one of 6 subcategories proposed by Dana Point Classification, accounts for approximately half of PAH cases and up to 40% of patients with no family history carries mutations in the bone morphogenetic protein receptor type 2 (BMPR2) gene." (PMID 23157700, 2012).
pulmonary arterial hypertension (continued). "Previous studies indicate that patients with pulmonary arterial hypertension (PAH) carrying a mutation in the bone morphogenetic protein receptor type 2 (BMPR2) gene, develop the disease 10 years earlier than non-carriers, and have a more severe hemodynamic compromise at diagnosis." (PMID 20534176, 2010). "The exception is BMPR2, which is involved in pulmonary hypertension, rather than essential hypertension." (PMID 16551372, 2006). "The Registry to Evaluate Early and Long-Term Pulmonary Arterial Hypertension Disease Management (REVEAL) showed a higher female predominance of PAH irrespective of BMPR2 status, and found that the female-to-male ratio for PAH was 3.9:1 in races other than whites, black and Hispanic." (PMID 34900561, 2021). "The bone morphogenetic protein receptor type-II or BMPR2 is a plasmatic membrane protein that transduces extracellular signals through the formation of heteromeric complexes, and their dysregulation plays a role during pulmonary hypertension vascular remodeling and endothelial dysfunction." (PMID 34867473, 2021). "Reduced or absent BMPR2 expression was observed in the lung vasculature of patients with idiopathic PAH (iPAH, then called primary pulmonary hypertension) and hPAH." (PMID 32521690, 2020).
pulmonary hypertension (87 papers, 2006 to 2025). Increased pressure within the pulmonary circulation due to lung or heart disorder. "Mutation and deficiency of BMPR2 leads to an obvious perivascular inflammation and muscularization in pulmonary hypertension." (PMID 37886639, 2023). "According to the report from the most recent World Symposium on Pulmonary Hypertension germline mutations in the gene encoding BMPRII (BMPR2) are detected in 70–80% of patients with a familial history of PAH, heritable PAH." (PMID 34198654, 2021). "This resulted to 72% of PAH patients carrying a BMPR2 mutation in the cohort reported by Austin and colleagues, as compared to 17% in the cohort from the New York Presbyterian Pulmonary Hypertension Center, and 25% in the French PAH network." (PMID 20534176, 2010). "As a national referral center for the diagnosis, treatment, and follow-up of patients with pulmonary hypertension, our unit has identified a 9.4% prevalence of epithelial neoplasms in a cohort of 32 patients with heritable PAH due to BMPR2 mutation." (PMID 40923964, 2025). "The role of Bmpr2 has also been extensively studied in models of pulmonary hypertension (PH) using genetically modified mice." (PMID 35395852, 2022). "Dysfunctional BMPR2 signaling recapitulates the cellular abnormalities in PAH as well as the pathobiology in experimental pulmonary hypertension (PH)." (PMID 33374819, 2020). "Cavin-1 and BMPR2 competitively interact with the Caveolin-1 scaffolding domain that modulate BMP/Smad signal transduction in pulmonary artery endothelial cells and these interactions are involved in the development of pulmonary hypertension." (PMID 38182755, 2024). "In this study, we analyzed 7 PAH-causing genes including BMPR2, ACVRL1, ENG, SMAD9, CAV1, KCNK3, and CBLN2 in 49 CTEPH patients and 17 patients recovered from pulmonary embolism (PE) but without pulmonary hypertension(PH)." (PMID 26820968, 2016). "Not only are deleterious mutations in BMPR2 associated with both heritable (~80%) and idiopathic (~20%) PAH, but decreased BMPR2 expression and signaling has also been demonstrated in other subtypes of PAH and non-PAH pulmonary hypertension (PH) in the absence of mutations." (PMID 33233517, 2020).